SLC36A1 (solute carrier family 36 member 1)
Description:
Electrogenic proton/amino acid symporter with selectivity for small apolar L-amino acids, their D-enantiomers and selected amino acid derivatives such as 4-aminobutanoate/GABA. May be involved in the efflux from the lysosomal compartment of neutral amino acids resulting from proteolysis (By similarity). May play a role in specifying sites for exocytosis in neurons (By similarity).
Synonyms: PAT1; LYAAT-1; TRAMD3; Dct1; LYAAT1
Tractability: Antibody: UniProt places it where antibodies can reach, with high confidence; its Gene Ontology location is reachable by antibodies, with high confidence; UniProt predicts a signal peptide or a membrane-spanning region. PROTAC: its protein half-life has been measured.
Target class: Electrochemical transporter; SLC superfamily of solute carriers; Transporter; SLC36 family of proton-coupled amino acid transporters
Gene: Protein-coding gene on chromosome 5 (151,437,046 to 151,492,379, forward strand). Ensembl gene ENSG00000123643.
Subcellular location: Cell membrane; Apical cell membrane; Lysosome membrane
Pathways (Reactome):
Transport of small molecules: Amino acid transport across the plasma membrane; Proton-coupled neutral amino acid transporters
Gene Ontology:
Molecular function: ABC-type taurine transporter transporter activity; alanine transmembrane transporter activity; amino acid:proton symporter activity; proline:proton symporter activity; protein binding; amino acid transmembrane transporter activity; gamma-aminobutyric acid:proton symporter activity; glycine transmembrane transporter activity; L-alanine transmembrane transporter activity; L-proline transmembrane transporter activity; neutral L-amino acid transmembrane transporter activity; proton transmembrane transporter activity
Biological process: alanine transport; amino acid import across plasma membrane; taurine transmembrane transport; amino acid transport; glycine transport; L-alanine transport; proline transmembrane transport; proton transmembrane transport; gamma-aminobutyric acid transport; neutral amino acid transport
Cellular component: apical plasma membrane; endoplasmic reticulum; lysosomal membrane; plasma membrane; lysosome
Genetic constraint (gnomAD): Loss-of-function variants: 24 observed, 45.81 expected, observed/expected ratio (o/e) 0.52, 90% interval 0.38 to 0.74. The upper end of that interval is the gene's LOEUF score, 0.74, which puts it in group 3 of 6, group 1 being the genes least tolerant of losing a copy. Missense variants: 514 observed, 625.13 expected, observed/expected ratio (o/e) 0.82, 90% interval 0.76 to 0.88. Synonymous variants: 255 observed, 259.6 expected, observed/expected ratio (o/e) 0.98, 90% interval 0.89 to 1.09.
Homologues: Orthologues: chimpanzee SLC36A1 (99% identical), macaque SLC36A1 (99% identical), dog SLC36A1 (94% identical), rabbit SLC36A1 (92% identical), pig SLC36A1 (87% identical), mouse Slc36a1 (86% identical), rat Slc36a1 (86% identical), guinea pig SLC36A1 (80% identical), tropical clawed frog slc36a1 (67% identical), zebrafish slc36a1 (59% identical), Drosophila melanogaster CG13384 (41% identical), Drosophila melanogaster CG16700 (33% identical), and 15 more. Paralogues in human: SLC36A2 (71% identical), SLC36A3 (60% identical), SLC36A4 (54% identical), SLC38A3 (21% identical), SLC38A4 (21% identical), SLC38A1 (20% identical), SLC38A2 (20% identical), SLC32A1 (18% identical), SLC38A5 (18% identical), SLC38A10 (16% identical), SLC38A6 (16% identical), SLC38A7 (16% identical), and 3 more.
Diseases named in the same sentence as SLC36A1 in open-access papers:
SLC36A1 is named in the same sentence as 13 diseases in open-access papers, as found by Europe PMC text mining. Sharing a sentence is not in itself a finding about the gene and the disease. The quoted sentences say what the papers report.
colorectal tumors (2 papers, 2014 to 2024). "Another study showed that SLC36A1 carries mutations in primary colorectal tumors, and more than 10% of the investigated colorectal cell lines and SLC36A1 mutations have also been reported in other primary tumors in the TCGA database." (PMID 38399253, 2024).
melanoma (2 papers, 2022 to 2023). A malignant, usually aggressive tumor composed of atypical, neoplastic melanocytes. "A reactivation of mammalian target of rapamycin 1 (mTORC1) signaling by increasing expression of solute carrier family 36 member 1 (SLC36A1), contributes Palbociclib and Ribociclib resistance in Melanoma." (PMID 37475713, 2023).
colitis (1 paper, 2026). Inflammation of the colon. "Furthermore, the SLC36A1 agonist sarcosine enhances barrier homeostasis and attenuates colitis in mice, highlighting the diagnostic and therapeutic potential of this axis in UC." (PMID 41782409, 2026).
colorectal cancer (1 paper, 2014). A primary or metastatic malignant neoplasm that affects the colon or rectum. "Although the remaining 7 genes (PKD1, FAM38A, WDR81, TMEM136, SLC36A1, SLC26A6, IGFLR1) are mutated in >10% of the colorectal cancer cell lines, literature searches did not reveal evidence of the functional role or therapeutic potential of these genes in colorectal cancer." (PMID 25193853, 2014).
depression (1 paper, 2016). "Among them, the expression levels of CIDEC, RNASE1, SLC36A1, and STYXL1 mRNA were significantly changed depending on the state of depression in the RT-qPCR analysis, which was consistent with the results of the microarray analysis." (PMID 26926397, 2016).
ulcerative colitis (1 paper, 2026). An inflammatory bowel disease involving the mucosal surface of the large intestine and rectum. "Clinically, SLC36A1 expression inversely correlates with ulcerative colitis (UC) severity in human samples." (PMID 41782409, 2026).
Urea (1 paper, 2022). "SLC38A2 was the only one glycine transporter detected in No Wash sample, whereas SLC6A9 and SLC36A1 were specifically found in Urea Wash sample." (PMID 35085786, 2022).
cancer (6 papers, 2021 to 2025). A tumor composed of atypical neoplastic, often pleomorphic cells that invade other tissues. "Overall, the role of the proton-coupled amino acid transporter SLC36A1 in cancer is still unclear; however, as it has been found to activate mTORC1, it cannot be ruled out that SLC36A1/PAT1 has one or more roles in cancer metabolism and development." (PMID 38399253, 2024). "Similarly, the Kaplan–Meier plots of these cancer patients showed a poor prognosis with higher expression levels of NRF3, SLC36A1, SLC38A9, RagC, each RAB5 isoforms, and SLC7A1 genes." (PMID 36818298, 2023). "The SLC36A1, SLC7A5, SLC7A8 genes, which are related to amino acid transmembrane transporter activity, could play a role in tumour uptake of amino acids produced by host protein degradation during cancer cachexia and contribute to the growth of tumors." (PMID 36428623, 2022).
tumour (6 papers, 2019 to 2022). "SLC36A1, also known as PAT1, has been linked to tumor cell growth through its involvement in the activation of mTORC1." (PMID 31949161, 2020). "By selecting competitive, non-transported inhibitors of SLC36A1 from this study, we performed a whole-animal Drosophila screen to identify candidates that suppress tumour growth and display minimal whole-animal toxicity." (PMID 32938923, 2020).
SLC36A1 also shares sentences with these, for which no sentence is quoted: Anxiety (1 paper); mesothelioma (1); pancreatic adenocarcinoma (1); Tay-Sachs disease (1).